CXCR6 (C-X-C motif chemokine receptor 6)
Description:
Receptor for the C-X-C chemokine CXCL16. Used as a coreceptor by SIVs and by strains of HIV-2 and m-tropic HIV-1.
Synonyms: CD186; BONZO; STRL33; TYMSTR; CDw186
Tractability: Small molecule: a high-quality ligand is known; it belongs to a druggable protein family. Antibody: its Gene Ontology location is reachable by antibodies, with high confidence; UniProt places it where antibodies can reach, with medium confidence; UniProt predicts a signal peptide or a membrane-spanning region. PROTAC: a small molecule that binds it is known.
Target class: Peptide receptor (family A GPCR); Membrane receptor; Family A G protein-coupled receptor; CXC chemokine receptor; Chemokine receptor
Gene: Protein-coding gene on chromosome 3 (45,940,933 to 45,948,353, forward strand). Ensembl gene ENSG00000172215.
Subcellular location: Cell membrane
Pathways (Reactome):
Signal Transduction: Chemokine receptors bind chemokines; G alpha (i) signalling events
Gene Ontology:
Molecular function: protein binding; C-C chemokine binding; C-C chemokine receptor activity; coreceptor activity; G protein-coupled receptor activity; C-X-C chemokine binding; C-X-C chemokine receptor activity; chemokine receptor activity
Biological process: calcium-mediated signaling; cell chemotaxis; G protein-coupled receptor signaling pathway; immune response; positive regulation of cytosolic calcium ion concentration; viral genome replication; chemokine-mediated signaling pathway; chemotaxis; inflammatory response
Cellular component: external side of plasma membrane; plasma membrane; membrane
Genetic constraint (gnomAD): Loss-of-function variants: 6 observed, 7.92 expected, observed/expected ratio (o/e) 0.76, 90% interval 0.41 to 1.48. That is too few expected variants to judge how well the gene tolerates losing a copy. Missense variants: 326 observed, 439.5 expected, observed/expected ratio (o/e) 0.74, 90% interval 0.68 to 0.81. Synonymous variants: 171 observed, 169.86 expected, observed/expected ratio (o/e) 1.01, 90% interval 0.89 to 1.14.
Homologues: Orthologues: chimpanzee CXCR6 (99% identical), macaque CXCR6 (95% identical), dog CXCR6 (81% identical), pig CXCR6 (80% identical), rabbit CXCR6 (75% identical), mouse Cxcr6 (75% identical), rat Cxcr6 (72% identical), guinea pig CXCR6 (65% identical). Paralogues in human: CCR6 (35% identical), CCR9 (34% identical), CCR7 (33% identical), ACKR4 (32% identical), CXCR4 (31% identical), CXCR2 (30% identical), CCR1 (30% identical), CCR5 (30% identical), CX3CR1 (30% identical), CCR4 (30% identical), CCR3 (29% identical), CXCR3 (29% identical), and 11 more.
Diseases named in the same sentence as CXCR6 in open-access papers:
CXCR6 is named in the same sentence as 191 diseases in open-access papers, as found by Europe PMC text mining. Sharing a sentence is not in itself a finding about the gene and the disease. The quoted sentences say what the papers report.
COVID-19 (65 papers, 2020 to 2026). A disease caused by infection with severe acute respiratory syndrome coronavirus 2. "Since rs71327024 is an eQTL for the CXCR6 gene that has several RNA splice variants, we had to choose an isoform expressed predominantly in T helpers, well known players in COVID-19 pathogenesis." (PMID 37762093, 2023). "We recently showed that CXCR6, previously identified as a risk allele for severe COVID-19, is associated with COVID-19 mortality in hospitalized patients, potentially mediated through cardiac involvement." (PMID 38089856, 2023). "We showed that impaired c-Myb binding at the rs71327024(T) allele results in reduced CXCR6 transcription, providing a possible explanation for the harmful effect of this single-nucleotide variant in the context of COVID-19 pathogenesis." (PMID 37762093, 2023). "Our data suggest a possible mechanistic link explaining the association of the minor rs71327024(T) allele with COVID-19 severity through reduced CXCR6 expression, which is observed in T cells of SARS-CoV2 infected patients." (PMID 37762093, 2023). "Of these genes, 7 are chemokine receptor genes (CCR1, CCR2, CCR3, CCR5, CCR9, CCRL2, and CXCR6), which are likely linked to the segment’s association with COVID-19 severity." (PMID 36763080, 2023). "A similar pattern was observed for CXCR6 in lung, indicating that carriers of the introgressed segment have increased risk of severe COVID-19." (PMID 35318325, 2022). "This QTL shows conserved synteny with a locus in humans on Chr3 (which includes Ccr9 and Cxcr6) that was identified in COVID-19 human Genome-wide Association Studies (GWAS) predicting severe outcome and hospitalization." (PMID 35862771, 2022). "A specific genetic locus including immune-related genes (such as C-X-C motif chemokine receptor 6—CXCR6), was found to be associated with worse prognosis in COVID-19 patients." (PMID 33674591, 2021). "Two of these genes, CCR9 and CXCR6, were also found within the set of COVID-19 associated genes, while CCR5 and PIGN genes were novel." (PMID 34557504, 2021). "Our findings identify SLC6A20 and CXCR6 as putative causal genes that modulate COVID-19 risk and highlight the usefulness of this integrative approach to bridge the divide between correlational and causal studies of human biology." (PMID 34425859, 2021). "Given that CXCR6 was recently associated with severe COVID-19 presenting with respiratory failure, we also analyzed its correlation with sex and viral load." (PMID 34027897, 2021). "Note that the gene encoding CXCR6 is one of six genes located within the 3p21.31 locus strongly associated with severe COVID-19 in a recent genome-wide association study." (PMID 32989174, 2020). "A recent gene wide association study showed rs11385942 at locus 3p21.3121 that includes the CXCR6 gene was associated with severe COVID-19 respiratory." (PMID 33298930, 2020). "We conclude that a disrupted c-Myb binding site may decrease CXCR6 expression in T helper cells of individuals carrying the minor rs71327024(T) allele and thus may promote the progression of severe COVID-19 and other inflammatory pathologies." (PMID 37762093, 2023). "Taken together, dysregulation of T lymphocyte migration to the lungs due to reduced expression of CXCR6 may provide an explanation for the exacerbated condition of COVID-19 patients harboring the risk rs71327024(T) variant." (PMID 37762093, 2023). "In the present work, we have shown that the disrupted c-Myb binding site in the 3p21.31 locus may decrease CXCR6 expression in T helper cells of individuals carrying the risk rs71327024(T) allele and promote the progression of severe COVID-19." (PMID 37762093, 2023). "A set of studies of eQTLs (expression quantitative trait loci) reveals that the COVID-19 severity may be mediated by genetic variants associated with CXCR6 expression." (PMID 37762093, 2023).
COVID-19 (continued). "According to GeneAtlas, FYCO1 variant rs33910087 is a highly significant modifier of monocyte percentage (p = 3.85 × 10−46), and based on GTEx v8, this variant is also an eQTL for several protein-coding genes previously associated with COVID-19 (CXCR6, FYCO1, SLC6A20, CCR1, LZTFL1)." (PMID 35910207, 2022). "By integrating the results of CRISPR screen and cis-eQTLs, we have identified SLC6A20 and CXCR6 as potential protein-coding genes in the 3p21.31 locus through which noncoding variants associated with COVID-19 risk in human patients may function." (PMID 34425859, 2021). "Additionally, our analysis shows a lung CXCR6+ effector memory T cell subset is associated with better prognosis in patients with severe COVID-19." (PMID 33674591, 2021). "A severe COVID-19 GWAS Group has identified genetic variants linked to genes such as SLC6A20, LZTFL1, CCR9, FYCO1, CXCR6, and XCR1 in patients experiencing respiratory failure due to COVID-19." (PMID 40143318, 2025). "We did not observe changes in the expression of any of the six genes clustered in the locus associated with respiratory failure in patients with COVID-19 (CCR9, SLC6A20, LZTFL1, CXCR6, XCR1, FYCO1)." (PMID 40722786, 2025). "The first and most significant locus described in GWAS associated with COVID-19 critical is 3p21.31, which encompasses six genes (SLC6A20, LZTFL1, CCR9, FYCO1, CXCR6, and XCR1) (The Severe COVID-19 GWAS Group, 2020)." (PMID 38226654, 2024). "A recent study developed by our research group investigated genetic variants present in the genes SLC6A20, LZTFL1, CCR9, FYCO1, CXCR6, XR1 and ABO involved with the severity of COVID-19 in indigenous people." (PMID 38543725, 2024). "Recent studies revealed that the CXCR6/CXCL16 axis plays an important role in severe COVID-19 immunopathogenesis." (PMID 37762093, 2023). "CXCR6 expression by lung-resident memory CD8+ T cells was lower in patients with severe COVID-19, indicating the possible protective role of CXCR6+ killer T cells." (PMID 37762093, 2023). "In COVID-19, CXCR6 expression is reduced in lung resident memory T cells from patients with severe disease as compared to the control cohort with moderate symptoms." (PMID 37762093, 2023). "In this regard, a gene cluster on chromosome 3 containing CCR1, CCR3, CXCR6, and CCR9, has been identified as a major risk factor for COVID-19 at the genome-wide level (Zeberg and Pääbo, 2020)." (PMID 36320810, 2022). "Together, the results indicate that the major subsets affected during moderate infection with COVID-19 or influenza are lymphocytes expressing CXCR3 as well as CXCR6 and CCR5." (PMID 35371005, 2022). "In total, several GWAS in humans have identified a common locus on Chr3 (3p21.31), that identified six genes associated with COVID-19 severity, susceptibility, respiratory failure, and risk of hospitalization and included CCR9 and CXCR6 (14, 15, 32, –, 34)." (PMID 35862771, 2022). "This study aimed to associate genetic variants in the SLC6A20, LZTFL1, CCR9, FYCO1, CXCR6, XCR1, and ABO genes with the risk of severe forms of COVID-19 in Amazonian Native Americans, and to compare the frequencies with continental populations." (PMID 35455670, 2022). "We identified putative causal genes, including SLC6A20, CXCR6, CCR9, and CCR5 in the locus on 3p21.31, quantifying their effect on mediating expression and on severe COVID-19." (PMID 35318325, 2022). "For carriers of the archaic segment, the higher risk of severe COVID-19 was driven mainly by the genetic regulation of the expression of CCR5 and CXCR6 in lung." (PMID 35318325, 2022). "By performing a MAGMA gene-level association analysis, we observed that 25 genes including CXCR6, CCR1, IFNAR2, IL10RB, and OAS1 were significantly associated with severe COVID-19 (FDR < 0.05)." (PMID 35172892, 2022). "When compared to healthy controls, a trend towards a loss of CXCR3+ in COVID-19 and loss of CXCR3+ and CXCR6+ NK cells in influenza patients was observed." (PMID 35371005, 2022).
COVID-19 (continued). "We demonstrated that CXCR6+ memory CD8+T cells mounted highly effective immune responses to against COVID-19, highlighting the remarkable biological plasticity in subsets of memory CD8+T cells differentiation." (PMID 35172892, 2022). "Our data indicate a universal role for CXCR3-mediated lung-homing of NK cells and T cells in COVID-19 and influenza and an additional role for recruitment via CXCR6 and CCR5 in CD8+ T cells." (PMID 35371005, 2022). "Similar to CCR1− CD16+monocytes, we observed no remarked difference of cellular interactions between normal controls and COVID-19 patients among CXCR6− memory CD8+T cells (P > 0.05)." (PMID 35172892, 2022). "The first COVID-19 genome-wide association study identified the 3p21.31 gene cluster, including “SLC6A20, LZTFL1, CCR9, FYCO1, CXCR6, and XCR1” as a genetic susceptibility locus in severe patients with COVID-19 and respiratory failure." (PMID 37521836, 2022). "The eQTL analysis encompassing 22 lead SNPs identified 29 novel genes in addition to 4 genes (i.e., SLC6A20, FYCO1, CXCR6, CCR1) previously reported by the severe COVID-19 GWAS group to be associated with rs11385942 at locus 3p21.31." (PMID 34027315, 2021). "Two loci associated with respiratory failure in COVID-19 were found, one of which was the GA-G insertion-deletion variant in locus 3p21.31 that is composed of six genes (SLC6A20, LZTFL1, CCR9, FYCO1, CXCR6, and XCR1)." (PMID 33791232, 2021). "Several other loci show no previously documented genome-wide significant associations, despite the high significance and attractive candidate genes for COVID-19 (for example, CXCR6, LZTFL1, IFNAR2 and OAS1/OAS2/OAS3 loci)." (PMID 34237774, 2021). "Moreover, CCR1 was reported to be expressed by CD16+ monocytes, while CCR5, CCR9, and CXCR6 by T cell subsets in COVID-19 patients." (PMID 39811276, 2025). "In a study correlating gene and protein expression of 17 COVID-19 susceptibility genes with lung cancer prognosis, it was found that the hyperexpression of FYCO1, CXCR6, XCR1, and TAC4 in cancer cells was protective, whereas that of TMEM65 and OAS1 was a risk factor for SARS-CoV2 infection." (PMID 41375068, 2025). "Another study found that the genetic predisposition to colorectal or lung cancer was causally associated with a decreased or increased susceptibility to COVID-19 severity, respectively, and this association pointed to the LZTFL1, CCR9, FYCO1, CXCR6, XCR1, and ABO genes." (PMID 41375068, 2025). "In addition, according to single-nucleus RNA-seq data, CXCR6 expression was dysregulated in lung samples from the cohort of patients who have died from COVID-19, with marked downregulation in some of the samples." (PMID 37762093, 2023). "Also, recently, it was found that a region of our DNA situated on chromosome 3 (locus 3p21.31), spanning a length of 49.3 kb, consisting of 6 genes (SLC6A20, LZTFL1, CCR9, FYCO1, CXCR6, and XCR1), was associated with the risk of developing severe COVID-19." (PMID 37929242, 2023). "Of interest, CXCR6+ CD8+ T lymphocytes in the lungs have been associated with long-lasting COVID-19 inflammation and might play a role in long COVID-19." (PMID 36829456, 2023). "Moreover, patients with severe COVID-19 have fewer lung-resident memory CD8+ T cells with lower expression of CXCR6, and their lung macrophages produced less CXCL16 compared to moderately ill patients." (PMID 37762093, 2023). "Notably, we prioritized 34 risk genes, including potential causal genes of CXCR6, CCR1, and ABO, to be associated with severe COVID-19." (PMID 35172892, 2022). "Six genes (namely, SLC20A6, CCR9, CXCR6, CCR2, CCR5, and CCR5AS) were significant from the MR-JTI analysis after Bonferroni correction, indicating causal support for these genes on COVID-19 hospitalization." (PMID 35318325, 2022).
COVID-19 (continued). "The first GWAS analysis with 1980 patients with COVID-19 identified two loci associated with the most severe forms of COVID-19: one locus was 3p21.31, which includes the genes SLC6A20, LZTFL1, CCR9, FYCO1, CXCR6, and XCR1, while the other was 9q34.21, including the ABO blood group." (PMID 35455670, 2022). "The present study investigated genetic variants in the SLC6A20, LZTFL1, CCR9, FYCO1, CXCR6, XCR1, and ABO genes that are potentially related to severe forms of COVID-19 in Amazonian Native American populations, and compared their frequencies with continental populations." (PMID 35455670, 2022). "Notably, four chemokine receptors identified by our study (CXCR6 in the ileum, CCR1/2 and CCR9 in both ileum and colon) are coded in a genomic region found to be a COVID-19 risk locus on chromosome 3, further validating our predictions." (PMID 35501398, 2022). "Similarly to NK cells also CD8+ T cells expressing CXCR6 were reduced in patients with severe COVID-19, while Aiolos cell density was upregulated." (PMID 33060840, 2021). "This locus contained six genes (SL6A20, LTZFL1, CCR9, FYCO1, CXCR6 and CXR1) that could all plausibly be linked to COVID-19 pathophysiology on the basis of their known functions." (PMID 33339864, 2020). "A significantly higher frequency of the risk allele for severe COVID-19 was found on chromosome 3, which codes for the SIT1 amino acid transporter as well as receptors for inflammatory cytokines, CC-motif chemokine receptor 9 (CCR9) and the C-X-C motif chemokine receptor 6 (CXCR6) among other genes." (PMID 33142989, 2020). "The strongest and most consistent finding for COVID-19 severity is the 3p21.31 region containing multiple protein-coding genes, including LZTFL1, SLC6A20, FYCO1, and chemokine receptor genes (CCR9, CXCR6 and XCR1)." (PMID 38517939, 2024). "Through COVID-19-relevant transcriptome and enrichment gene sets, seven druggable targets with COVID-19-relevant functions were identified, including CCR9, CXCR6, XCR1, IL10RB, OAS1, OAS2, and OAS3." (PMID 37886583, 2023). "In patients with respiratory diseases, the CXCR6/CXCL16 axis is known to attract T cells to the lungs and this mechanism appears to play a role in the COVID-19 immunopathogenesis as well." (PMID 37762093, 2023). "Here, we compared changes in NK cell and T cell subset compositions, focusing on expression of the lung-homing receptors CXCR3, CXCR6, CCR2, and CCR5, in the peripheral blood from patients with clinically moderate COVID-19 or influenza." (PMID 35371005, 2022). "With regard to CXCR6+ memory CD8+T cells in PBMCs, the predicted cell-to-cell interactions showed an elevation with increased severities of COVID-19 (P < 0.05)." (PMID 35172892, 2022). "To gain refined insights into CCR1+ CD16+monocytes and CXCR6+ memory CD8+T cells, we examined the cellular interactions among cell populations in PBMCs and BALFs according to the COVID-19 disease status using the CellChat algorithm." (PMID 35172892, 2022). "Overall, these results indicated that CXCR6+ memory CD8+T cells have an enhanced propensity to be multi-functional and activated T cells involved in severe COVID-19." (PMID 35172892, 2022). "In contrast, CXCR6, CCR2, and CCR5 were most highly expressed on TEM cells both in healthy controls and COVID-19 patients." (PMID 35371005, 2022). "Overall, T cells displayed similar expression patterns as NK cells in terms of lower frequencies of CXCR3+ CD8+ T cells in COVID-19 patients and of CXCR3+ and CXCR6+ CD8+ T cells in influenza patients." (PMID 35371005, 2022). "Frequencies of NK cells and T cells expressing CXCR3, CXCR6, and CCR5 were altered in peripheral blood of COVID-19 and influenza patients, in line with increased transcript expression of CXCR3, CXCR6, and CCR5 and their respective ligands in BAL fluid." (PMID 35371005, 2022).